NLRP3 (NLR family pyrin domain containing 3)
Diseases named in the same sentence as NLRP3 in open-access papers (continued):
Sharing a sentence is not in itself a finding about the gene and the disease.
colitis (continued). "This study aimed to investigate whether NLRP3 deficiency or glyburide, a sulfonylurea used for diabetes management and known as an NLRP3 inhibitor, could suppress colitis and its related colorectal tumorigenesis." (PMID 39519191, 2024). "The investigation focused on assessing whether the oral administration of GLB inhibits colitis and its associated tumor development in the inflamed colorectum by modulating NLRP3, with NLRP3-deficient mice serving as the control group." (PMID 39519191, 2024). "Thus, the NLRP3 inflammasome is considered instrumental in resistance to colitis-associated tumorigenesis." (PMID 37081882, 2023). "In addition, the activation of Ral, a member of the Ras subfamily, promoted the development of colitis-associated CRC by activating the NLRP3 inflammasome." (PMID 37833958, 2023). "Colitis has been shown to be less severe in NLRP3‐deficient mice than in wild‐type mice." (PMID 36840499, 2023). "Furthermore, IL-18 secretion mediated by the NLRP3 inflammasome can indirectly inhibit the tumor progression of colitis-associated colorectal cancer by inducing regulatory T (Treg) cells to produce IFN-γ and enhancing the cytotoxicity of T cells and NK cells." (PMID 37497237, 2023). "In support of our finding are two previous reports that a CAPS mouse transgenic model carrying human NLRP3 pathogenic mutations maintain homeostasis in the gut microbiota and are resistant to experimental colitis, whereas NLRP12 defect results in microbiome disturbance and colitis." (PMID 38343435, 2023). "A study in 2017 found that the anomalously activated NLRP3 inflammasome caused the local increased production of IL-1β, induced regulatory T cells and maintained gut homeostasis through remodeling the gut microbiota to resist the colitis." (PMID 37833958, 2023). "Similarly, genetically modified mice carrying the Nlrp3 R258W mutation, which induces hyperactivation of NLRP3 inflammasome, were strongly resistant to experimental colitis." (PMID 35185922, 2022). "The NLRP3 inflammasome is an important part of innate immunity that resists the invasion of pathogenic microorganisms, and defect or excessive inhibition of inflammasomes leads to more severe colitis." (PMID 35330829, 2022). "It has been shown that the hemolysin secreted from P. mirabilis can predispose to more severe colitis by activating NLRP3 and IL-1ß secretion while ability of A. muciniphila to degrade intestinal mucin facilitates the activation of NLRP6 in genetically susceptible individuals." (PMID 35381031, 2022). "To clarify whether the protective effect of A. muciniphila in colitis depends on NLRP3, we performed the NLRP3-deficient assay in NLRP3−/− mice in vivo." (PMID 34612661, 2021). "Emerging studies provide evidence that some genetic abnormalities might induce enhanced NLRP3 inflammasome activation and cause colitis." (PMID 33808793, 2021). "Also, platelet activating factor receptor regulates lung inflammation caused by colitis by NLRP3 inflammation." (PMID 34409047, 2021). "Furthermore, E. faecalis suppressed the activation of NLRP3 inflammasome, and thereby protected animals from intestinal inflammation in dextran sodium sulfate-induced colitis-associated colorectal cancer." (PMID 34992527, 2021). "Therefore, the function of NLRP3 in mucosal immunity and colitis seems to be complex, with unclear underlying mechanism." (PMID 34628369, 2021). "Consistently, NLRP3 activation can reduce the initiation of colitis-associated cancer." (PMID 33821998, 2021). "NLRP3 deficiency eliminates the protective effect of A. muciniphila in colitis." (PMID 34612661, 2021). "Taken together, these results indicated that ROS-induced mitochondrial damage might be a dominant mechanism of underlying activation of the NLRP3 inflammasome in colitis by treatment with Schisandrin B through AMPK/Nrf2 signaling pathway." (PMID 34628369, 2021).
colitis (continued). "They found that the hyperactive NLRP3 inflammasome, associated with local over-production of IL-1β, could maintain gut homeostasis resulting in strong resistance to experimental colitis." (PMID 34692718, 2021). "The data showed that the expression of miR-223 was increased in biopsies from active IBD patients and that miR-223-deficient mice exhibit exacerbated experimental DSS-colitis characterized by increased NLRP3 inflammasome activation, and elevated IL1β production in the colon." (PMID 33808793, 2021). "Nevertheless, using REV-ERBα –/– mice, increased NLRP3 and IL-1β expression was detected, and REV-ERBα was linked to experimental colitis through its ability to repress the expression of p65 subunit of NFkB, which subsequently leads to the suppression of NLRP3 inflammasome at the priming level." (PMID 33717162, 2021). "This follows recent reports showing that IL-1β and IL-18 production can provide protection against colitis, and supported by recent GWAS studies showing that the polymorphisms which confer hypofunctional NLRP3 phenotypes are associated with the development of IBD." (PMID 34692718, 2021). "In contrast, NLRP3-deficient mice induced with colitis released more IL-17." (PMID 32716024, 2020). "In NLRP3 KO mice, with increased susceptibility to colitis, the development of potentially pathogenic bacteria, such as Citrobacter, Proteus, and Shigella spp., was observed, and Changes in β-defensin levels were most likely responsible for changes in microbiota composition." (PMID 33143375, 2020). "Inhibition of NLRP3 affects the microbiota and makes the intestine more susceptible to colitis." (PMID 33143375, 2020). "Importantly, the transgenic mice exhibited intestinal inflammatory responses and increased susceptibility to colitis-associated cancer in an NLRP3 inflammasome-dependent manner." (PMID 32703253, 2020). "Xu’s lab reported that NLRP3 inflammasome is mediated by mitophagy in colitis-associated cancer." (PMID 33240089, 2020). "Autophagy and NLRP3 inflammasome were associated with the process of colitis." (PMID 33240089, 2020). "However, the role of NLRP3 in colitis is controversial, several studies reported that NLRP3 deficiency exerts a protective effect in DSS induced colitis." (PMID 32950971, 2020). "Our findings indicate that application of the inactivated probiotic, E. faecalis, may be a useful and safe strategy for attenuation of NLRP3-mediated colitis and inflammation-associated colon carcinogenesis." (PMID 30823406, 2019). "As the NLRP3 inflammasome appears to enhance the development of colitis, it has been recommended as potential therapeutic target for the prevention of colitis and colitis-associated CRC." (PMID 30823406, 2019). "Besides, NLRP3−/− mice with an increased susceptibility to colitis showed that altered B-defensins levels were most likely due to an altered microbiota composition in gut." (PMID 30873162, 2019). "The influence of the NLRP3 inflammasome appears controversial in colitis-associated colon cancer." (PMID 31439870, 2019). "Next, we analyzed whether increased Nlrp3 inflammasome activation is the cause for exacerbated outcomes of DSS-induced colitis in Irgm1 knockout mice." (PMID 30612879, 2019). "The aim of this study is to assess whether a widely used probiotic Enterococcus faecalis can modulate the NLRP3 inflammasome and protect against colitis and colitis-associated CRC." (PMID 30823406, 2019). "Genetic ablation of genes of NLRP3 components are predisposed to colitis and colorectal cancer." (PMID 29872077, 2018). "A less esoteric setting of NLRP3 hyperactivity is colitis occurring in the presence of IL-10 deficiency which is due to the fact that IL-10 has the unique ability among commonly produced cytokines to inhibit the NLRP3 inflammasome and thus to cause hyperactivity of this inflammasome in its absence." (PMID 30455704, 2018). "Contrasting with wild-type mice, Nlrp3-deficient mice were resistant to DSS-induced colitis." (PMID 30315268, 2018).
colitis (continued). "However, other studies have shown an association of increased NLRP3 with the promotion and metastasis of gastric cancer, enhanced proliferation and migration of lung cancer cells, and colitis-associated colon cancer." (PMID 28663562, 2017). "Additionally, administration of recombinant IL-18 can induce remission in colitis-associated injuries and suppress the progression of colorectal tumor in Nlrp3/Caspase1-deficient mice." (PMID 28360909, 2017). "However, some groups got contradictory results that Nlrp3-deficient mice treated with DSS exhibited attenuated colitis and reduced infiltration of immune cells." (PMID 28360909, 2017). "Additionally, Nlrp6 and Nlrp3 have been shown to negatively regulate colitis-associated tumorigenesis." (PMID 29120406, 2017). "Furthermore, neutralizing IL-15 normalized the susceptibility of Nlrp3−/− mice to DSS-induced colitis, an effect that was associated with reduced expression of IL-17 in colonic tissues." (PMID 27610005, 2016). "NLRP3 as well as caspase-1-deficient mice were protected from DSS-induced colitis." (PMID 27965665, 2016). "Also, mice deficient in NLRP3 were more susceptible to either DSS or TNBS-induced colitis and exhibited decreased IL-1β as well as decreased beta-defensins." (PMID 24115947, 2013). "In addition, ASC and caspase-1 knockout mice are also susceptible to DSS-induced colitis and colitis-associated colon cancer, suggesting that the activation of the NLRP3 inflammasome may have an inhibitory effect on colorectal carcinogenesis." (PMID 37497237, 2023). "Given the recently demonstrated ability of Adam8 to control neutrophil transmigration and NLRP3 inflammasome activation, the processes tightly associated with colon inflammation, Adam8 can be considered as a novel promising master regulator of colitis and CAC; this requires further clarification." (PMID 36901742, 2023). "Similarly, NLRP3-deficient mice are susceptible to colitis-associated cancer." (PMID 36932407, 2023). "Thus, the NLRP3 inflammasome may play a role in regulating a delicate immune balance in the colon, loss or overactivation of NLRP3 may both break down the balance and thus lead to the onset of colonic inflammation." (PMID 36090968, 2022). "Furthermore, this Nlrp3 mutation increases the number of locally potent anti-inflammatory Treg cells that maintain intestinal homeostasis and protect the host against experimental colitis and CRC." (PMID 35954484, 2022). "A number of recent reports demonstrate that the overactivation of NLRP3 inflammasome caused by various genetic abnormalities lead to development of colitis, whereas some other studies provide evidence that deficiency of NLRP3 and inflammasome related genes may induce more severe colitis in mice." (PMID 36090968, 2022). "Moreover, NLRP3 deficiency negated the protective effect of A. muciniphila in colitis." (PMID 34612661, 2021). "Finally, we show that NLRP3 inflammasome is implicated in Cg-induced colitis in mice." (PMID 32894139, 2020). "Protein levels of mature IL-1β and cleaved caspase-1 were increased in colon tissues of Slco2a1-knockout mice treated with DSS, which led us to hypothesize that NLRP3 inflammasome activation might contribute to the exacerbation of DSS colitis in Slco2a1-deficient mice." (PMID 32184453, 2020). "To determine whether the loss of NLRP3 inflammasome function and the resulting increased susceptibility to experimental colitis were driven by changes in T cell phenotype, we assessed the expression of IL-10 in CD4+ and CD8+ T cell populations isolated from the colonic LP." (PMID 27610005, 2016). "However, whether the loss of NLRP3 inflammasome function within the intestinal epithelium or mucosal immune cells contributes to the increased susceptibility to colitis is still a subject of debate." (PMID 27610005, 2016). "However, NLRP3-deficiency led to resistance to DSS-colitis in a different study." (PMID 24381573, 2013).
colitis (continued). "Therefore, we hypothesized that binding of TXNIP to NLRP3 activates the inflammasome, which causes autocleavage of caspase-1 and the release of mature cytokines IL-1 beta and IL-18 during colitis." (PMID 23915129, 2013). "Its mechanism involves regulating the NOX2/ROS/mitochondria/NLRP3 axis and altering gut microbiota composition, providing novel insights for colitis treatment." (PMID 41901297, 2026). "In conclusion, spermine exhibited treatment efficacy on DSS-induced colitis by inhibiting NLRP3-mediated inflammatory response, promoting mitophagy and improving intestinal microbial dysbiosis." (PMID 41900936, 2026). "Animal models and clinical validation: TLR blockers reduce inflammatory mediators; NLRP3 inhibitors significantly improve experimental colitis by reducing the secretion of IL-1β and IL-18." (PMID 41495287, 2026). "Collectively, our results support the conclusion that Lac16 suppresses NLRP3 inflammasome overactivation and alleviates colitis in a gut microbiota-dependent manner." (PMID 41171006, 2025). "The NLRP3 inflammasome has an important role in infectious enteritis and colitis, and protection from intestinal pathogens." (PMID 41149694, 2025). "Collectively, these findings demonstrate that isobutyric acid, a microbiota-derived SCFA, plays a pivotal role in suppressing NLRP3 inflammasome overactivation and mediates the protective effects of Lac16 against colitis pathogenesis." (PMID 41171006, 2025). "A previous study has shown that NLRP3 is a direct binding partner for the autophagy inhibitor mTOR and in colitis mice, hypoxia ameliorated intestinal inflammation by reducing NLRP3-mTOR binding and thus activating autophagy." (PMID 39936902, 2025). "Overall, our findings indicate that DA ameliorates DSS-induced colitis by reducing oxidative stress, dampening Mapk-driven inflammatory signaling pathways, and inhibiting Nlrp3 inflammasome activation and subsequent pyroptosis." (PMID 41301498, 2025). "GL-V9, an agonist of the small molecule adenosine 5′-monophosphate-activated protein kinase (AMPK), significantly degrades the NLRP3 inflammasome complex in macrophages by inducing autophagy, thereby preventing colitis." (PMID 40842999, 2025). "The NLRP3 inflammasome is also involved in inflammatory bowel disease, colorectal cancer, changes in the gut microbiome, and colitis and enteritis." (PMID 41149694, 2025). "To further elucidate the pathological contributions of the NLRP3 inflammasome in Prdx1-mediated colitis, we employed the NLRP3 inhibitor MCC950 in a DSS-induced acute colitis model." (PMID 40715057, 2025). "In the current research, Lac16 significantly suppressed NLRP3 inflammasome overactivation in colitis." (PMID 41171006, 2025). "There is evidence that miR- 223 - 3p-mediated activation of the NLRP3 inflammasome and pyroptosis are involved in the development of colitis; targeting NLRP3 inhibits Staphylococcus aureus-induced inflammasome activation and pyroptosis." (PMID 40360974, 2025). "Collectively, these findings demonstrate that BMSCs-Exo alleviates DSS-induced colitis in mice by suppressing NLRP3-mediated pyroptosis, offering a mechanistic basis for its protective role against intestinal inflammation and injury." (PMID 40661945, 2025). "In this respect, it was demonstrated that, in NLRP3-deficient mice, the proliferation rate of epithelial cells in the colon during acute DSS colitis was significantly reduced." (PMID 40227443, 2025). "Clioquinol directly inhibits NLRP3 inflammasome activation, reduces macrophage inflammatory factor production, and alleviates experimental sepsis, colitis and acute peritonitis." (PMID 40211890, 2025). "The deubiquitinase OTUD6A in macrophages exacerbates intestinal inflammation and colitis by activating the NLRP3 inflammasome." (PMID 39809743, 2025).
colitis (continued). "Our findings suggested that LCA, modulated by O. splanchnicus, significantly inhibited the infiltration of neutrophils and NETosis by decreasing the expression of the NLRP3‐GSDMD axis in colitis mice." (PMID 40990446, 2025). "The pseudo-germ-free mouse model confirmed that Lac16 inhibits NLRP3 inflammasome overactivation and ameliorates colitis symptoms by modulating the gut microbiota." (PMID 41171006, 2025). "In colitis, mice infected with Helicobacter pylori activate NLRP3 and IL-18 processing, which is sought to protect against colon inflammation." (PMID 41376623, 2025). "We found the activation of the nuclear receptor REV-ERBα alleviates experimental colitis by inhibiting the NF-κB/NLRP3 pathway." (PMID 41467030, 2025). "IL-18, which is released when the NLRP3 inflammasome in the gut epithelium is activated by elevated amounts of SCFAs produced by the GM, has a protective effect against colitis and contributes to gut homeostasis." (PMID 40796700, 2025). "Collectively, our findings highlight GB1 as a promising therapeutic candidate for colitis treatment, primarily through NLRP3 inflammasome suppression and intestinal barrier restoration." (PMID 40362256, 2025). "The administration of TiO2 NPs induced more severe intestinal injury in colitis mice via NOD-like receptor family pyrin-containing 3 (NLRP3) overactivation and ROS excessive production." (PMID 41008252, 2025). "The colitis group showed a significant increase in both colon mTOR content and NLRP3 gene expression, with 3.61‐fold (F = 528.4, p < 0.0001) and 3.68‐fold (F = 66.14, p < 0.0001) increases, respectively, compared to the normal control group." (PMID 40387460, 2025). "In a previous study, selective CB2 receptor agonist HU308 was found to inhibit the NLRP3 inflammasome in mouse peritoneal macrophages and an experimental colitis mouse model." (PMID 41230096, 2025). "A significant upregulation of Nlrp3 mRNA expression was observed in the DSS-induced colitis model compared to the control group, further supporting its role in colonic inflammation." (PMID 40995471, 2025). "This study addressed this gap by focusing on the role of UAF1 and its potential interaction with NLRP3 in the context of colitis." (PMID 39966502, 2025). "Molecular docking studies have suggested that FXR serves as a target for Nigakinone, and inhibition of FXR diminishes the protective effects of Nigakinone, highlighting its role in the modulation of the FXR/NLRP3 signaling pathway in the context of colitis." (PMID 40271055, 2025). "In colitis, oral dysbiosis resulting from Enterobacter species induces robust release of pro-inflammatory cytokines as a result of macrophage NLRP3 activation." (PMID 41376623, 2025). "In conclusion, the present study indicated that the m6A-forming enzyme METTL3 controls UAF1 stabilization, promoting inflammation in the mouse model of colitis by enhancing NLRP3." (PMID 39966502, 2025). "They found that activation of the NLRP3 inflammasome in epithelial cells by G protein-coupled receptor signaling protects against dextran sodium sulfate-induced colitis." (PMID 41149694, 2025). "In pseudo-germ-free mice with antibiotic-induced microbiota depletion, Lac16 showed impaired ability to suppress NLRP3 inflammasome overactivation and ameliorate colitis." (PMID 41171006, 2025). "In DSS colitis, NLRP3-driven oxidative stress upregulates Bax and downregulates Bcl-2, thereby promoting apoptosis." (PMID 40995471, 2025). "In colitis models, the modulation of Th1/Th2 and Tregs/Th17 cell balance, alongside the inhibition of the NLRP3 inflammasome, remodeled the gut microbiota, providing new therapeutic strategies for patients with colitis." (PMID 40491914, 2025). "Administration of NDGA alleviated experimental colitis by downregulating the GSDMD/NR4A1/NLRP3 axis-mediated macrophage pyroptosis." (PMID 40596758, 2025).